CSF1R (colony stimulating factor 1 receptor)
Description:
Tyrosine-protein kinase that acts as a cell-surface receptor for CSF1 and IL34 and plays an essential role in the regulation of survival, proliferation and differentiation of hematopoietic precursor cells, especially mononuclear phagocytes, such as macrophages and monocytes. Promotes the release of pro-inflammatory chemokines in response to IL34 and CSF1, and thereby plays an important role in innate immunity and in inflammatory processes. Plays an important role in the regulation of osteoclast proliferation and differentiation, the regulation of bone resorption, and is required for normal bone and tooth development. Required for normal male and female fertility, and for normal development of milk ducts and acinar structures in the mammary gland during pregnancy. Promotes reorganization of the actin cytoskeleton, regulates formation of membrane ruffles, cell adhesion and cell migration, and promotes cancer cell invasion. Activates several signaling pathways in response to ligand binding, including the ERK1/2 and the JNK pathway. Phosphorylates PIK3R1, PLCG2, GRB2, SLA2 and CBL. Activation of PLCG2 leads to the production of the cellular signaling molecules diacylglycerol and inositol 1,4,5-trisphosphate, that then lead to the activation of protein kinase C family members, especially PRKCD. Phosphorylation of PIK3R1, the regulatory subunit of phosphatidylinositol 3-kinase, leads to activation of the AKT1 signaling pathway. Activated CSF1R also mediates activation of the MAP kinases MAPK1/ERK2 and/or MAPK3/ERK1, and of the SRC family kinases SRC, FYN and YES1. Activated CSF1R transmits signals both via proteins that directly interact with phosphorylated tyrosine residues in its intracellular domain, or via adapter proteins, such as GRB2. Promotes activation of STAT family members STAT3, STAT5A and/or STAT5B. Promotes tyrosine phosphorylation of SHC1 and INPP5D/SHIP-1. Receptor signaling is down-regulated by protein phosphatases, such as INPP5D/SHIP-1, that dephosphorylate the receptor and its downstream effectors, and by rapid internalization of the activated receptor. In the central nervous system, may play a role in the development of microglia macrophages.
Synonyms: CSF-1R; M-CSF-R; CD115; FMS; C-FMS; CSFR; BANDDOS; FIM2; GPSC; HDLS; HDLS1
Tractability: Small molecule: an approved drug acts on it; a structure with a bound ligand is known; a high-quality ligand is known; it has a high-quality binding pocket; it belongs to a druggable protein family. Antibody: a drug acting on it is in phase 2 or 3 trials; its Gene Ontology location is reachable by antibodies, with high confidence; UniProt places it where antibodies can reach, with medium confidence; UniProt predicts a signal peptide or a membrane-spanning region; the Human Protein Atlas places it where antibodies can reach. PROTAC: UniProt records ubiquitination sites on it; ubiquitination databases record sites on it; a small molecule that binds it is known.
Target class: TK protein kinase group; Kinase; Tyrosine protein kinase PDGFR family; Protein Kinase; Enzyme
Chemical probes: AC710, AZ683, BLZ-945 (high quality), pexidartinib (high quality), vimseltinib (high quality)
Gene: Protein-coding gene on chromosome 5 (150,053,291 to 150,113,372, reverse strand). Ensembl gene ENSG00000182578.
Subcellular location: Cell membrane
Subcellular location (Human Protein Atlas): Plasma membrane; Vesicles
Pathways (Reactome):
Immune System: Other interleukin signaling; Signaling by CSF1 (M-CSF) in myeloid cells
Gene expression (Transcription): Transcriptional Regulation by VENTX
Gene Ontology:
Molecular function: cytokine binding; macrophage colony-stimulating factor receptor activity; protein binding; growth factor binding; protein tyrosine kinase activity; ATP binding; protein homodimerization activity; protein kinase activity; protein phosphatase binding; transmembrane receptor protein tyrosine kinase activity
Biological process: cell population proliferation; cell-cell junction maintenance; cellular response to macrophage colony-stimulating factor stimulus; cytokine-mediated signaling pathway; hemopoiesis; peptidyl-tyrosine phosphorylation; positive regulation of cell motility; positive regulation of cell population proliferation; positive regulation of chemokine production; positive regulation of macrophage chemotaxis; positive regulation of macrophage proliferation; positive regulation of protein phosphorylation; positive regulation of protein tyrosine kinase activity; protein autophosphorylation; regulation of cell shape; cell migration; cell surface receptor protein tyrosine kinase signaling pathway; cellular response to cytokine stimulus; inflammatory response; innate immune response; macrophage colony-stimulating factor signaling pathway; macrophage differentiation; mammary gland duct morphogenesis; monocyte differentiation; osteoclast differentiation; and 23 more
Cellular component: CSF1-CSF1R complex; plasma membrane; receptor complex; cell surface; membrane
Genetic constraint (gnomAD): Loss-of-function variants: 42 observed, 112.02 expected, observed/expected ratio (o/e) 0.37, 90% interval 0.29 to 0.49. The upper end of that interval is the gene's LOEUF score, 0.49, which puts it in group 2 of 6, group 1 being the genes least tolerant of losing a copy. Missense variants: 1,052 observed, 1,290.8 expected, observed/expected ratio (o/e) 0.81, 90% interval 0.77 to 0.86. Synonymous variants: 523 observed, 521.99 expected, observed/expected ratio (o/e) 1, 90% interval 0.93 to 1.08.
Gene-disease validity (ClinGen):
ClinGen rates the evidence that CSF1R causes each of these diseases.
leukoencephalopathy, diffuse hereditary, with spheroids 1 (autosomal dominant): Definitive. A rare autosomal dominant disease characterized by a complex phenotype including progressive dementia, apraxia, apathy, impaired balance, parkinsonism, spasticity and epilepsy.
Homologues: Orthologues: chimpanzee CSF1R (99% identical), macaque CSF1R (87% identical), dog CSF1R (84% identical), guinea pig CSF1R (81% identical), pig CSF1R (80% identical), rat Csf1r (77% identical), mouse Csf1r (75% identical), rabbit CSF1R (72% identical), tropical clawed frog csf1r (45% identical), zebrafish csf1ra (43% identical), zebrafish csf1rb (37% identical), zebrafish si:zfos-1069f5.1 (10% identical). Paralogues in human: KIT (39% identical), PDGFRB (34% identical), PDGFRA (33% identical), FLT3 (31% identical), KDR (30% identical), FLT1 (29% identical), FLT4 (28% identical), FGFR2 (23% identical), FGFR3 (22% identical), FGFR1 (22% identical), FGFR4 (22% identical), ALK (19% identical), and 41 more.
Diseases named in the same sentence as CSF1R in open-access papers:
CSF1R is named in the same sentence as 410 diseases in open-access papers, as found by Europe PMC text mining. Sharing a sentence is not in itself a finding about the gene and the disease. The quoted sentences say what the papers report.
breast cancer (149 papers, 2009 to 2026). A primary or metastatic malignant neoplasm involving the breast. "CSF-1 and its receptor (CSF-1R) assist in the regulation of macrophages; CSF-1R and/or CSF-1 expressions are potentially associated with a poor breast cancer prognosis." (PMID 39309874, 2024). "An earlier study demonstrated that CSF-1R+ breast cancer cells were associated with a worse prognosis and tumor spread, mostly in ER+ breast cancer." (PMID 38254773, 2024). "The anti-proliferative activity of kusunokinin observed in breast cancer cells was associated with the suppression of the CSF-1R and AKT pathways." (PMID 38254773, 2024). "Overexpression of CSF1 and CSF1R in a variety of tumors, including breast cancer, is associated with poor patient prognosis, thus suggesting that overexpression of CSF1R is associated with diseases such as cancer." (PMID 36770611, 2023). "It has been reported that high expression of CSF1R is related to breast cancer progression and that high rates of ErbB2 is linked to lower overall survival rates." (PMID 36014478, 2022). "In breast carcinoma cells, CSF-1R has been demonstrated as being functional and implicated in various biological effects, such as proliferation, invasion, and epithelial-mesenchymal transition." (PMID 36555673, 2022). "In patients with breast cancer, upregulation of CSF-1 and CSF-1 receptor (CSF-1R) is associated with inferior prognosis." (PMID 34359674, 2021). "We report the prognostic significance of CSF-1R protein expression on carcinoma cells and tumor-associated macrophages in a large, well-characterized cohort of early breast cancer patients." (PMID 34830923, 2021). "Breast cancers with high expressions of CSF-1R on carcinoma cells are associated with significantly poor breast cancer-specific survival compared to tumors with low expression (HR 1.63; 95% CI 1.26–2.09; p < 0.001)." (PMID 34830923, 2021). "A high level of CSF-1 or CSF-1R expression in the tumor or peri-tumor tissue has been associated with poor patient survival in lymphoma, breast cancer, and hepatocellular carcinoma." (PMID 31878087, 2019). "A high level of CSF-1 or CSF-1R expression in the tumour or peri-tumoral tissue has been associated with poor patient survival in different malignancies such as lymphoma, breast cancer and hepatocellular carcinoma." (PMID 31331034, 2019). "The same group also identified macrophages as a primary source of IL-10 and that inhibition of IL-10 receptor induced reduction of the breast cancer tumour burden if combined with chemotherapy, with an equivalent effect caused by blockade of CSF-1R." (PMID 31331034, 2019). "In cervical and mammary carcinoma mouse models, the depletion of tumor-associated macrophages, obtained by means of a highly selective Csf1r inhibitor, resulted in the arrest or delay of tumor growth." (PMID 31695671, 2019). "CSF-1R has been associated with mammary cancer aggressiveness in dogs, and the expression of the receptor has been shown to be increased in canine mammary adenocarcinoma cells in co-cultures with macrophages." (PMID 26174804, 2015). "Expression of the CSF1R is associated with increased radio-resistance of breast cancer cell lines, and high levels of this receptor are associated with local breast cancer recurrence after radiation therapy in women." (PMID 24019961, 2013). "During the course of our previous studies we found the CSF-1R expression in canine mammary cancer cells, as well as in tumour-associated macrophages." (PMID 22353646, 2012). "As an example, administration of the CSF-1R inhibitors in combination with checkpoint blockade-based immunotherapy causes a delay in tumor progression in mouse models of various cancers, including breast cancer." (PMID 39003350, 2024). "Indeed, PARPi in combination with STING agonists demonstrated superior anti-tumor efficacy than PARPi combined with macrophage depletion via anti-CSF1R in our syngeneic GEMM of Brca1-deficient breast cancers." (PMID 35641483, 2022).
breast cancer (continued). "High carcinoma CSF-1R is associated with aggressive breast cancer biology and poor prognosis, particularly in ER+ cases, and identifies patients in whom biomarker-directed CSF-1R therapies may yield superior therapeutic responses." (PMID 34830923, 2021). "Given that CSF-1R inhibitors are under investigation in clinical trials, including in breast cancer, CSF-1R expression and association with immune biomarkers could identify patients who derive greater benefit from combination with immunotherapies." (PMID 34830923, 2021). "The finding that high levels of IL-34 are associated with better prognosis in certain breast cancer subtypes is surprising, since the expression of CSF-1 and the common receptor CSF-1R has been linked to aggressive behavior and poor prognosis in breast cancer patients." (PMID 29796177, 2018). "The signal-transduction pathways involving vascular endothelial growth factor receptor (VEGFR), platelet-derived growth factor receptor (PDGFR), stem-cell factor receptor (KIT), and colony stimulating factor-1 receptor (CSF-1R) have been implicated in breast cancer pathogenesis." (PMID 24914410, 2014). "We previously demonstrated that Src activation regulates a subset of phenotypic alterations induced by the colony stimulating factor 1 receptor tyrosine kinase (CSF-1R), which has been implicated in the progression of multiple types of carcinoma including breast cancer." (PMID 21049007, 2010). "We sought to test the hypothesis that the expression of CSF-1R protein on carcinoma cells will identify tumors with aggressive features and provide prognostic information in ER+ breast cancers, identifying a subgroup of patients associated with poor clinical outcome." (PMID 34830923, 2021). "We investigated the small-molecule receptor tyrosine kinase-inhibitor of colony-stimulating factor-1 receptor pexidartinib in the stage II/III breast cancer in the I-SPY2 platform trial." (PMID 39625569, 2025). "CSF-1R is highly expressed in a variety of tumor cells, including lung cancer, breast cancer, lymphoma, cervical cancer and so on." (PMID 40007537, 2025). "CSF-1/CSF-1R inhibitors have been identified as therapeutic targets for a variety of malignant tumors, such as glioma, hepatocellular carcinoma, breast cancer, lung cancer and pancreatic cancer, and have broad application prospects in tumor immunotherapy." (PMID 40007537, 2025). "With regard to breast cancer, mouse experiments have suggested that CSF1R inhibitors alone or in combination with chemotherapy can be used to treat TNBC." (PMID 39780291, 2025). "In canine mammary cancer cells, CSF-1R inhibition increased apoptosis and decreased Ki-67 positivity, suggesting that CSF-1R supported the survival and growth of cancer cells." (PMID 38254773, 2024). "In experimental models of breast cancer, inhibitors of CSF1R signaling have been shown to enhance the effectiveness of chemotherapy or radiotherapy by suppressing tumor growth and the spread of cancer to other parts of the body." (PMID 39309874, 2024). "The expression of csf1r gene, which produces CSF1R and CSF1, is strongly associated with poor outcome in breast cancer and results in tumor cell invasiveness and pro-metastatic behavior both in patient and in vitro." (PMID 38822100, 2024). "This work demonstrated the expression of CSF-1R transcripts in endometrial, ovarian and breast cancer cells." (PMID 38254773, 2024). "In canine mammary tumor cells, a genetic blockade of CSF-1R negatively affected the migratory and invasive abilities of these cells." (PMID 38254773, 2024). "Similar effects have been observed in studies on oral and breast cancers; CSF-1R inhibitor monotherapy resulted in depletion of M2 macrophages and an increase in CD8- and CD4-positive T cells, despite not suppressing tumor growth." (PMID 39000110, 2024).
breast cancer (continued). "PLX3397 (Pexidarnitib), another anti-CSF1R antibody, is also being investigated along with eribulin for the treatment of brain metastatic cases of breast cancer (NCT01596751)." (PMID 38715072, 2024). "By reprogramming the TME and TAMs, CSF-1R inhibitors enhance the eradication of breast cancer by T-cell-mediated mechanisms." (PMID 39309874, 2024). "Previous work demonstrated CSF-1R expression at the membrane and in the nucleus of CSF-1-stimulated cervical, ovarian and breast cancer cell lines." (PMID 38254773, 2024). "In vitro and in vivo studies indicated that IL-34/CSF-1R activation increased BrdU incorporation, colony forming abilities of breast cancer cells and tumor growth in mouse models." (PMID 38254773, 2024). "High expression levels of CSF1 and CSF1R were related to breast cancer progression and poor prognosis." (PMID 37097499, 2023). "In the development of breast cancer, the use of inhibitors targeting the colony-stimulating factor 1 receptor (CSF1-R) can eliminate TAMs, leading to effective inhibition of metastasis and angiogenesis, as well as reduction in tumor invasiveness." (PMID 37445965, 2023). "Among them, drugs affecting the M-CSF/CSF1R axis and PI3Kγ are being tested in advanced solid tumors, glioblastoma, sarcoma, breast cancer, and renal cell carcinoma." (PMID 36380627, 2023). "In this study, we demonstrate, for the first time, that treating established syngeneic murine colon and breast carcinoma tumors with a CSF1R-blocking antibody also promotes the expansion of neoepitope-specific T cells." (PMID 37505292, 2023). "Transgenic mice overexpressing CSF-1 in their mammary epithelium presented an increased breast cancer metastatic potential, while overexpression of CSF-1/CSF-1R in human ovarian and breast carcinoma correlates with poor survival outcomes." (PMID 35804859, 2022). "In breast cancer models, the efficacy of paclitaxel (Taxol) was enhanced by CSF1R inhibitor–mediated TAM depletion." (PMID 35664746, 2022). "In mouse models of cervical cancer and breast cancer, the depletion of TAMs achieved with highly selective CSF-1R inhibitors led to tumor growth arrest or delay." (PMID 35326625, 2022). "Colony-stimulating factor 1 receptor (CSF1R) is another emerging cell surface target for breast cancer." (PMID 35807438, 2022). "(±)KU inhibits the proliferation of breast cancer cells through the suppression of CSF1R and its downstream signaling molecules, including AKT, cyclinD1 and CDK1." (PMID 36552555, 2022). "These statements validated the use of racemic trans-(±)-kusunokinin as a potential candidate or developed scaffold for targeting CSF1R and other proteins in the CSF1R breast cancer progression pathway." (PMID 35807438, 2022). "CSF-1R is thus a prime target for treating solid tumors such as prostate or breast cancer alone or in combination with chemotherapy or radiation therapy." (PMID 36555673, 2022). "Breast cancer is the most consistently documented type of cancer concerning the expression and function of CSF-1R." (PMID 36555673, 2022). "Accordingly, depletion of TAMs with anti-CSF1/CSF1R (CSF1 receptor) antibodies enhanced chemosensitivity to a combinatorial chemotherapeutic approach in human breast cancer xenografts and a genetic mammary tumor model." (PMID 35664746, 2022). "Activation of this pathway or a higher expression of either CSF-1 or CSF-1R results in poor prognosis of breast cancer in postmenopausal women." (PMID 34207035, 2021). "CSF-1 expression is associated with poor prognosis and increased infiltration of CSF-1 receptor (CSF-1R)-expressing macrophages in mouse models of breast cancer." (PMID 33968034, 2021). "Other caveats to anti-CSF-1R therapies include reports showing that inhibition of CSF-1R signaling can promote breast cancer metastasis." (PMID 33968034, 2021). "CSF1R inhibition was shown to reduce to breast cancer cell invasion and lead to antitumor efficacy in melanoma-BrM and intracerebrally inoculated breast cancer cells." (PMID 34539650, 2021).